SOX10 (SRY-box transcription factor 10)
Diseases named in the same sentence as SOX10 in open-access papers (continued):
Sharing a sentence is not in itself a finding about the gene and the disease.
myoepithelial tumor (8 papers, 2021 to 2025). A benign or malignant tumor characterized by the presence of cells that show myoepithelial differentiation. "SOX-10 and S1009 expression was detected in all pleomorphic adenomas and myoepitheliomas, and in 11 of the 74 oncocytomas." (PMID 39684268, 2024). "Other soft tissue neoplasms: Myoepithelial tumors display epithelioid or spindle cytology with S100-protein and SOX10 immunoreactivity." (PMID 34943200, 2021). "Furthermore, although EWSR1::ATF1 is associated with multiple tumors, including angiomatoid fibrous histiocytoma, myoepithelial tumors, hyalinizing clear cell carcinoma, and CCS-like tumors of the gastrointestinal tract, SOX10 expression is relatively specific to CCS." (PMID 37405123, 2023). "Furthermore, SOX10 is frequently positive in myoepithelioma,9) but was also negative in this case." (PMID 40766037, 2025). "In addition, SOX10, a transcription factor that plays a key role in the differentiation of the neural crest, maintenance of Schwann cells and melanocytes, and that was recently found to be expressed in myoepithelial tumors, was also not detected." (PMID 35094698, 2022).
brain tumors (7 papers, 2018 to 2024). "Compared to cross-sectional TNBCs, SOX10 was over-represented in brain-metastatic cases, with SOX10 status concordant in ~90% of matching brain tumours." (PMID 35501337, 2022). "Comparative genomics revealed that the zebrafish RB1 brain tumors are most similar to the human OLIG2+/SOX10+ CNS-PNET subtype." (PMID 29914980, 2018). "In addition, analysis of a curated brain tumor stem cell transcriptome dataset (n = 144, 116 independent lines) indicated that SOX10-low brain tumor stem cells are enriched for qNSC and quiescent stem cell tumor cell signature (Fig. EV3F), validating the association of SOX10-low and NSC-like state." (PMID 39285246, 2024). "Together, these results demonstrate the zebrafish rb1 brain tumors have a highly proliferative, poorly differentiated state with an oligoneural precursor molecular signature found in human OLIG2+/SOX10+ and zebrafish NRAS CNS-PNETs." (PMID 29914980, 2018). "Non-ERMS head tumors highly expressed sox10 and gfap and immunohistochemistry staining confirmed that these brain tumors express high levels of Sox10 and Gfap." (PMID 37266578, 2023). "However, the combination of strong immunopositivity for both, SOX10 and ANKRD55 proved highly specific for CNS_NBL, both in institutionally diagnosed CNS-PNET cohort and extended set of malignant pediatric brain tumors." (PMID 33536079, 2021). "Therefore, in contrast to SOX10, ANKRD55 has not been systematically tested for its expression in human brain tumors." (PMID 33536079, 2021).
prostate carcinoma (7 papers, 2018 to 2025). A carcinoma that arises from epithelial cells of the prostate gland. "Sox10 has been suggested to function as a tumor suppressor in digestive cancers and in prostatic carcinoma since it was silenced or down-regulated in these tumors." (PMID 29695285, 2018). "SOX10 has been suggested as a useful marker for corresponding tumors, although it was usually silenced or downregulated in malignant tumors such as digestive cancers and prostatic carcinoma." (PMID 32677948, 2020). "SFPQ has been previously shown to regulate the stability of AR transcripts in prostate cancer and neurons and our own analysis of SFPQ-enriched transcripts identify SOX10 and the lncRNA, TMEM51-AS1 as being destabilised in SFPQ depleted cells." (PMID 34218270, 2021). "The gene expression of SOX in human prostate cancer tissue compared with non-cancerous revealed the fact that SOX7, SOX9, and SOX10 were associated with advance-stage prostate cancer, whereas SOX7 and SOX9 were identified as prognostic biomarker in prostate cancer." (PMID 30972102, 2019).
squamous cell carcinoma (7 papers, 2020 to 2025). A carcinoma arising from squamous epithelial cells. "It is remarkable that both tumors in our study revealed strong and diffuse expression of SOX10, suggesting that SOX10 might be of value in distinguishing porocarcinoma from squamous cell carcinoma on limited biopsies." (PMID 32436169, 2020). "The immunohistochemical features of HCCC of the salivary gland overlap with those of various salivary tumors, such as MEC and squamous cell carcinoma, all of which are positive for CK7, p63 and p40, and negativity for S-100 and SOX-10." (PMID 39958930, 2025). "All had characteristic interferon-ω autoantibodies, while most also had broader autoreactivity, including IL-22, 17α-hydroxylase, 21-hydroxylase, aromatic L-amino acid decarboxylase (AADC), tryptophan hydroxylase 1 (TPH1), SOX10, NALP5 and squamous cell carcinoma (SCC) antibodies." (PMID 41009535, 2025).
Waardenburg syndrome type 2 (7 papers, 2012 to 2025). Waardenburg syndrome type 2 (WS2) is an autosomal dominant subtype of Waardenburg syndrome (WS), characterized by varying degrees of deafness and pigmentation anomalies of eyes, hair and skin, but without dystopia canthorum. "Type 2 WS has been linked to pathogenic variants in the MITF, SNAI2, and SOX10 genes." (PMID 40650035, 2025).
acinic cell carcinoma (6 papers, 2020 to 2025). "SOX10-expressing neoplasms in the salivary glands include acinic cell carcinoma, epithelial-myoepithelial carcinoma, adenoid cystic carcinoma, and polymorphous adenocarcinoma." (PMID 38132479, 2023). "In the neoplastic counterpart, SOX10 is observed in a broad group of tumors as acinic cell carcinomas, adenoid cystic carcinomas, epithelial-myoepithelial carcinomas, myoepithelial carcinomas, basal cell adenoma and pleomorphic adenoma." (PMID 33591488, 2021). "Similarly, mucoepidermoid carcinoma was tested for S-100, SOX-10, and P63; acinic cell carcinoma was tested for SOX-10 and CK7; and adenoid cystic carcinoma was tested for markers, CD117, SOX-10, and Calponin, respectively." (PMID 38021816, 2023). "However, carcinomas may frequently display a diffuse oncocytic phenotype, being classified by their characteristic features (e.g., AR-positive salivary duct carcinoma, MEC with MAML2 rearrangements, secretory carcinoma with ETV6 NTRK3 gene fusion, and DOG1- and SOX10-positive acinic cell carcinoma)." (PMID 41440486, 2025). "Distinctively, acinic cell carcinoma can be differentiated from metastatic renal cell carcinoma in the parotid gland, as the latter does not express SOX10 on staining." (PMID 38132479, 2023).
granular cell tumor (6 papers, 2024 to 2026). An unusual benign or malignant neoplasm characterized by the presence of neoplastic large polygonal cells with granular, eosinophilic cytoplasm which contains abundant lysosomes. "Initial boring biopsy suggested a granular cell tumor based on morphology and SOX10/S100 positivity." (PMID 41536645, 2026). "In addition, the plump, polygonal tumor cells with intensely eosinophilic cytoplasm and visible mitotic figures closely resemble a malignant granular cell tumor (GCT), which can be distinguished by strong, diffuse S-100 and SOX10 expression in GCT and its rarity in deep soft tissue sites." (PMID 41179673, 2025). "Granular cell tumors are diffusely immunopositive for S100, SOX10 and inhibin, which are negative in ASPS." (PMID 37218666, 2024). "Positive immunohistochemical (IHC) staining for S-100, SOX10, and neuron-specific enolase (NSE), along with negative pan-keratin staining supported the diagnosis of a granular cell tumor with benign characteristics." (PMID 39224763, 2024).
nevus (6 papers, 2015 to 2022). Nevus (or naevus, plural nevi or naevi, from nævus, Latin for "birthmark") is the medical term for sharply circumscribed[1] and chronic lesions of the skin or mucosa. "Given thelocus' association with nevus count, SOX10, which encodes a member of theSOX (SRY-related HMG-box) family of transcription factors, is another candidate genein this locus." (PMID 26833246, 2016). "IHC staining of SOX10 and Ki67 demonstrated that the smaller the satellite nevus was, the more Ki67-positive cells were in the epidermis, indicating that small satellite nevi were in the proliferative phase, which might correspond to the early stage of lgCMN development." (PMID 36523350, 2022).
astrocytomas (5 papers, 2015 to 2023). "Therefore, Bannykh and colleagues decided to compare the presence of SOX10 in oligodendrogliomas and astrocytomas to determine its specificity." (PMID 36142793, 2022). "iPSC lines were first differentiated to forebrain-patterned SOX2+/NESTIN+/SOX10− neural progenitor cells (NPCs) and then to GFAP+ astrocytes, the cell-of-origin of astrocytoma, using a modified astrocyte differentiation protocol." (PMID 36973285, 2023).
bladder cancer (5 papers, 2018 to 2024). "SOX10 has also been associated with metaplastic bladder cancers, where it exhibits elevated expression in bladder cancer tissues compared to healthy tissue." (PMID 38132479, 2023). "We observed the bladder is also surrounded by an extensive glial network and Sox10 expression is associated with worse prognosis in bladder cancer, thus highlighting peripheral glial cells as important candidates for future investigation and integration into disease models of peripheral organs." (PMID 39621665, 2024). "Additionally, SOX10 has been identified in various epithelial neoplasms, including breast, ovarian, salivary gland, nasopharyngeal, and bladder cancers, presenting itself as a potential diagnostic and prognostic marker." (PMID 38132479, 2023). "The significance of SOX10 expression becomes evident when comparing its levels in different bladder cancers to normal bladder tissue." (PMID 38132479, 2023). "Knockdown experiments targeting SOX10 confirmed its prognostic value by significantly impacting the growth and metastatic ability of bladder cancer." (PMID 38132479, 2023). "Targeting SOX10 as a marker for diagnosis, prognosis, and treatment may prove useful in the context of bladder cancer." (PMID 38132479, 2023).
breast tumor (5 papers, 2019 to 2025). "In summary, our data indicate that the extent of promoter methylation loss in SOX10+ breast tumours correlates with their transcriptomic similarity to NCSCs—the earliest developmental cell state programmed by SOX10 activity and one synonymous with migration, multipotency and phenotypic plasticity." (PMID 35501337, 2022). "According to literature report, Mamglb, GATA binding protein 3 (GATA-3) and gross cystic disease fluid protein 15 (GCDFP-15) are less effective on proving the origin of salivary gland-type breast tumor, while SOX-10 may be more effective." (PMID 41040523, 2025). "Analysis of TCGA, METABRIC and ICGC breast tumour datasets showed SOX10 mRNA is expressed almost exclusively in TNBC, with a bimodal distribution suggesting distinct SOX10 positive and negative (+/−) subgroups." (PMID 35501337, 2022).
clear cell sarcoma (5 papers, 2021 to 2026). A rare malignant neoplasm with melanocytic differentiation characterized by the presence of polygonal or spindle shaped clear cells. "This study reveals the epigenetic and transcriptional suppression mechanism of the fusion oncogene EWSR1::ATF1 in clear cell sarcoma by histone deacetylase inhibitor treatment as well as identifying SOX10 as a transcription factor that regulates EWSR1::ATF1 expression." (PMID 37405123, 2023). "This is more obvious for clear cell sarcoma (definitionally with a melanocytic cell phenotype) and malignant gastrointestinal neuroectodermal tumor (coexpression of S100 and SOX10 but not specific melanocytic markers)." (PMID 37097347, 2023).
ependymoma (5 papers, 2018 to 2025). A WHO grade II, slow growing tumor of children and young adults, usually located intraventricularly. "SOX10 positivity supports PA diagnosis and helps distinguish it from ependymoma." (PMID 41458616, 2025). "Moreover, by considering TADs from cerebellum astrocytes, we can identify additional known ependymoma marker genes as EAGs, such as for example SOX10, due to their co-location with enhancer elements in the same TAD." (PMID 30704404, 2019). "Based on our re-analysis of the available gene expression and enhancer data across six intracranial ependymoma subgroups, we find that SOX10 is specifically expressed in the subgroup PF-EPN-A, likely regulated by a subgroup-specific enhancer element located ~ 40 Kbp upstream of the gene." (PMID 30704404, 2019). "In EWSR1-PLAGL1 fusion cases the absence of OLIG2 and SOX10 staining with relatively solid growth pattern are ependymal-like features, though ependymoma type EMA staining was only convincingly present in one case with focal/rare paranuclear dot-like staining in two cases." (PMID 39228008, 2024). "SOX10 functions in neural crest and oligodendrocyte development and has previously been described controversially as a negative marker for the diagnosis of ependymoma tumors." (PMID 30704404, 2019). "Indeed, the cases histopathologically presented as “mixed subependymomas-ependymomas” with well-circumscribed tumors exhibiting a diffuse immunoreactivity for GFAP, without expression of Olig2 or SOX10." (PMID 38581034, 2024).
gastrointestinal stromal tumor (5 papers, 2023 to 2025). "The definitive diagnosis of MPNST was confirmed through histopathology and a comprehensive immunohistochemical panel, which demonstrated characteristic spindle cells positive for S-100 and SOX-10 and negative for markers of gastrointestinal stromal tumors (GIST) and smooth muscle neoplasms." (PMID 40840072, 2025). "SOX10 expression is absent or minimal in gastrointestinal mesenchymal tumors with NTRK gene rearrangements, distinguishing them from gastrointestinal stromal tumors." (PMID 38132479, 2023).
lymphoma (5 papers, 2023 to 2026). A malignant (clonal) proliferation of B- lymphocytes or T- lymphocytes which involves the lymph nodes, bone marrow and/or extranodal sites. "We report the immunohistochemical results showing lymphoma cells staining positively for CD3 and CD30 and lacking expression of anaplastic lymphoma kinase, pan-cytokeratin, CD10, CD20, and SOX10." (PMID 37791178, 2023).
mesenchymal tumors (5 papers, 2023 to 2025). "Sox10 is consistently expressed in gastrointestinal nerve sheath tumors and can distinguish them from mesenchymal tumors that are interstitially S100 protein positive." (PMID 39213227, 2024). "In mesenchymal tumors, SOX10 expression serves as a valuable marker for distinguishing between different tumor types." (PMID 38132479, 2023). "In mesenchymal tumors, SOX10 expression becomes a valuable tool for distinguishing between different tumor types, thereby facilitating accurate diagnoses and informed treatment decisions." (PMID 38132479, 2023). "Notably, SOX10 expression is atypical for GLI1-altered mesenchymal tumours." (PMID 41035732, 2025). "We report a rare case of a pleural-based GLI1-altered mesenchymal tumour with a previously undescribed NCOR2::GLI1 gene fusion and unusual SOX10 positivity in a young adult with synchronous colorectal adenocarcinoma." (PMID 41035732, 2025). "Similar to the consistent immunoprofile of LMNA::NTRK1 driven human mesenchymal tumors, clone 1.14, although not clone 13, showed mRNA upregulation of S100 but no expression of SOX10." (PMID 36801905, 2023).
multiple sclerosis (5 papers, 2012 to 2025). A progressive autoimmune disorder affecting the central nervous system resulting in demyelination. "SOX10 has also been associated with alterations of the oligodendrocyte phenotype in relation with multiple sclerosis (MS)." (PMID 39982575, 2025). "The transcription factor SOX10 is a key regulator of myelinated glial cell phenotype and function, with a known role in multiple sclerosis (MS)." (PMID 39982575, 2025). "In support of our conclusions of SVZ-derived increased oligodendrogenesis, it has been reported that during multiple sclerosis PSA-NCAM+/Sox10+/Olig2+ triple-positive cells are detectable in the white matter of periventricular lesions in post-mortem human brain tissue." (PMID 22892385, 2012).
nerve sheath tumors (5 papers, 2022 to 2025). "This current immunohistochemical study explores a combined panel of laminin, Sox-10 and periaxin-1 as an ancillary diagnostic approach to confirm the diagnosis of suspect nerve sheath tumors." (PMID 36669002, 2022). "In our study, we histopathologically reevaluated 79 canine nerve sheath tumors and assessed their reactivity for the immunohistochemical markers Sox10, claudin-1, GFAP, CNPase, and Ki-67." (PMID 35622732, 2022). "The immunohistochemical profile showed CD34 positivity with S100 and SOX10 negativity, which is typical for DFSP and helps differentiate it from other spindle cell neoplasms such as nerve sheath tumors." (PMID 41466943, 2025). "Immunohistochemical staining, crucial for characterizing soft-tissue tumor differentiation, revealed diffuse positivity for SOX10 and S100 protein, consistent with a primary nerve sheath tumor rather than metastatic disease." (PMID 41306141, 2025).
neuropathy (5 papers, 2014 to 2023). A disorder affecting the nervous system that manifests with pain, tingling, numbness, and/or muscle weakness. "Specifically, these DEGs were associated with neuropathy-related pathways, such as GABRD, GABRP, TBX1, and SOX10, and inflammatory responses such as CXCL3, CXCL12, TNF, and IL6." (PMID 36147849, 2022). "Together, these lines of evidence suggest that modulating the SOX10-S100B axis may be a viable therapeutic target for various neuronal disorders including demyelinating disease, neuropathy, and nerve injury." (PMID 25536222, 2014).
pancreatic cancer (5 papers, 2018 to 2024). "The presence of SOX2 and SOX10 cancer stem cell markers in pancreatic tumor derived organoids delineates role of cancer stem cells in therapy resistance in pancreatic cancer." (PMID 36713532, 2022). "Immunohistochemistry showed that the pancreatic tumor cells were strongly positive for S100 (n = 6) and SOX10 (n = 2)." (PMID 33588954, 2021). "Further, positive identification of SOX2, SOX10 and TGFβ indicated presence of cancer stem cells in tumor organoids which might have some role in resistance to therapies in pancreatic cancer." (PMID 36713532, 2022). "Some genes do manifest this type of selectivity (e.g., broad dependence on CTNNB1 in colorectal cancer, MYB in leukemia, IRF4 in multiple myeloma, KRAS in pancreatic cancer, and SOX10 in skin cancer), but such common essentiality within a lineage is relatively unusual." (PMID 33554860, 2021). "Additional experiments demonstrated SOX10 and SOX2 (stem cell markers) expression in tumor organoids indicated may have some role in radiation and chemotherapy resistance in pancreatic cancer." (PMID 36713532, 2022).
skin cancer (5 papers, 2021 to 2024). "As expected, COSMIC signature 7, predominantly found in UV exposure-linked skin cancers, predicted dependency on module #20 (BRAF/MAPK1/MITF/SOX10) for cell survival." (PMID 37460547, 2023). "Across cancer types, STRN4 had a robust performance, which is in contrast to SOX10 that had a largely improved performance in skin cancer when compared to other cancer types." (PMID 33842927, 2021). "The vast majority of cancer cell lines that contributed to SOX10 dependency were derived from skin cancers." (PMID 33842927, 2021). "A substantial number of DDPs were enriched in melanogenesis which is due to the contribution of large number of SOX10’s DDPs and SOX10’s high level of dependency in skin cancers." (PMID 33842927, 2021). "The most obvious example was SOX10 which was dependent in >80% of skin cancer cell lines." (PMID 33842927, 2021).